CYP51A1 (cytochrome P450 family 51 subfamily A member 1)
Description:
Sterol 14alpha-demethylase that plays a critical role in the cholesterol biosynthesis pathway, being cholesterol the major sterol component in mammalian membranes as well as a precursor for bile acid and steroid hormone synthesis. Cytochrome P450 monooxygenase that catalyzes the three-step oxidative removal of the 14alpha-methyl group (C-32) of sterols such as lanosterol (lanosta-8,24-dien-3beta-ol) and 24,25-dihydrolanosterol (DHL) in the form of formate, and converts the sterols to 4,4-dimethyl-5alpha-cholesta-8,14,24-trien-3beta-ol and 4,4-dimethyl-8,14-cholestadien-3beta-ol, respectively, which are intermediates of cholesterol biosynthesis. Can also demethylate substrates not intrinsic to mammals, such as eburicol (24-methylene-24,25-dihydrolanosterol), but at a lower rate than DHL.
Synonyms: LDM; CYP51; CP51; CYPL1; P450L1; P450-14DM
Tractability: Small molecule: a structure with a bound ligand is known; a high-quality ligand is known; it has a high-quality binding pocket; it belongs to a druggable protein family. Antibody: UniProt predicts a signal peptide or a membrane-spanning region. PROTAC: UniProt records ubiquitination sites on it; ubiquitination databases record sites on it; its protein half-life has been measured; a small molecule that binds it is known.
Target class: Enzyme; Cytochrome P450 family 51A; Cytochrome P450 51A1; Cytochrome P450 family 51; Cytochrome P450
Gene: Protein-coding gene on chromosome 7 (92,084,987 to 92,134,803, reverse strand). Ensembl gene ENSG00000001630.
Subcellular location: Endoplasmic reticulum membrane; Microsome membrane
Subcellular location (Human Protein Atlas): Endoplasmic reticulum
Pathways (Reactome):
Metabolism: Activation of gene expression by SREBF (SREBP); Cholesterol biosynthesis via desmosterol (Bloch pathway); Endogenous sterols; Zymostenol biosynthesis via lathosterol (Kandutsch-Russell pathway)
Developmental Biology: EGR2 and SOX10-mediated initiation of Schwann cell myelination
Gene Ontology:
Molecular function: heme binding; sterol 14-demethylase activity; oxidoreductase activity, acting on paired donors, with incorporation or reduction of molecular oxygen, reduced flavin or flavoprotein as one donor, and incorporation of one atom of oxygen; iron ion binding; monooxygenase activity; oxidoreductase activity, acting on paired donors, with incorporation or reduction of molecular oxygen
Biological process: steroid biosynthetic process; cholesterol biosynthetic process; negative regulation of amyloid-beta clearance; negative regulation of protein catabolic process; negative regulation of protein secretion; sterol metabolic process; zymosterol biosynthetic process
Cellular component: membrane; endoplasmic reticulum membrane
Genetic constraint (gnomAD): Loss-of-function variants: 33 observed, 38.16 expected, observed/expected ratio (o/e) 0.86, 90% interval 0.65 to 1.16. The upper end of that interval is the gene's LOEUF score, 1.16, which puts it in group 5 of 6, group 1 being the genes least tolerant of losing a copy. Missense variants: 360 observed, 479.04 expected, observed/expected ratio (o/e) 0.75, 90% interval 0.69 to 0.82. Synonymous variants: 142 observed, 175.65 expected, observed/expected ratio (o/e) 0.81, 90% interval 0.7 to 0.93.
Homologues: Orthologues: chimpanzee CYP51A1 (99% identical), dog CYP51A1 (96% identical), pig CYP51A1 (94% identical), rat Cyp51 (92% identical), rabbit CYP51A1 (92% identical), mouse Cyp51 (90% identical), guinea pig CYP51A1 (88% identical), tropical clawed frog cyp51a1 (79% identical), zebrafish cyp51 (75% identical).